EPO (erythropoietin)
Diseases named in the same sentence as EPO in open-access papers (continued):
Sharing a sentence is not in itself a finding about the gene and the disease.
Stroke (continued). "There was a statistically significant difference between serum EPO levels in ischemic stroke patients with lacunar stroke compared to nonlacunar stroke ( 288.5 vs. 855.4 ng/mL; p = 0.021)." (PMID 38302546, 2024). "Due to stroke, HIF-1α and EPO starts to accumulate as a response to inadequate oxygen level." (PMID 38302546, 2024). "There was a relationship between the time of collection of blood and the level of EPO and also there was difference EPO level in lacunar stroke subtype compared with non-lacunar." (PMID 38302546, 2024). "Our dataset suggests that MBH and EPO combination therapy is an effective, minimally invasive, and acceptable treatment, even in the early period of patients with MMD or MMS following an acute stroke episode." (PMID 39764293, 2024). "On the contrary, increased risks of stroke and its subtypes were not reported with even large annual defined daily doses of erythropoietin in CKD." (PMID 37760839, 2023). "By rescaling the genetic associations to the PHI-induced effects of genetically predicted therapeutic rises in endogenous EPO levels, the odds of disease were 1.01 (95% CI = 0.93, 1.07) for CAD, 0.99 (95% CI = 0.87, 1.15) for MI, and 0.97 (95% CI = 0.87, 1.07) for stroke." (PMID 36055212, 2022). "A recent study on non-erythropoietic mutant erythropoietin (MEPO) showed that increased STAT3 phosphorylation was involved in the neuronal protection provided by MEPO in stroke mice using the specific inhibitor AG490 to block JAK2/STAT3 activation." (PMID 35578342, 2022). "- The injection of EPO-primed EPCs increased their homing ability and the cerebral blood flow as well as reduced the BBB disruption and cellular apoptosis at the ischemic hemisphere on day 14 post-stroke." (PMID 36158970, 2022). "Since little to nothing is known about the impact of EPO on microglia, microglial TAK1, and on the inflammasomes after stroke, we deemed an investigation of the reperfusion time point of 6 h after 30 min of tMCAo essential to draw any conclusion about a potential EPO/TAK1/inflammasome axis." (PMID 34628598, 2022). "One article reported that EPO did not protect brain tissue after stroke, and if the plasma level of EPO is too high, it is detrimental for elevating hematocrit and increases accompanying blood viscosity." (PMID 34366857, 2021). "It is therefore not surprising that EPO can determine a strong protective effect on neuronal tissue in experimental models of stroke, cerebral hemorrhage, traumatic brain injury, and neuroinflammatory and neurodegenerative diseases." (PMID 33790864, 2021). "In fact, not only the outcome of this non-rtPA subgroup and the first EPO stroke trial were promising." (PMID 32546125, 2020). "In another study, EPO administration did not affect recurrent stroke or mortality but improved long-term neurological outcome." (PMID 32733466, 2020). "For instance, upon inclusion (before study drug application), intent-to-treat non-rtPA patients receiving EPO, who died, suffered from much severer strokes as compared to placebo patients (NIHSS day 1: 20.4 ± 5.4 versus 13.3 ± 4.9; p = 0.003)." (PMID 32546125, 2020). "None of the patients receiving EPO experienced the potential adverse effects (hypertension crisis, MI, stroke and thromboembolic events) until discharge." (PMID 33680042, 2020). "The results therefore indicate that only hUCBC+EPO treatment may induce the enhancement of VEGF expression, the most significant factor in neurogenesis and angiogenesis, even in later stage post-stroke." (PMID 31024439, 2019). "Further subgroup analysis including post stroke biomarkers suggested that patients with ischemic stroke not receiving thrombolysis likely benefited from EPO treatment." (PMID 32038269, 2019). "This negative German Multicenter EPO Stroke Trial underscores the complexity posed by standard of care and difficulties in translating positive results from animal studies to the clinic." (PMID 32038269, 2019).
Stroke (continued). "In both cases (EGF and EPO infusion and CsA infusion), functional recovery was observed in the stroke-injured animals, suggesting that new neurons are not necessary for the behavioral recovery." (PMID 25056698, 2014). "Growths factors have been applied in stroke regeneration such as BDNF, GDNF and EPO." (PMID 25984331, 2014). "Nevertheless, exploratory subgroup analysis of the German Multicenter EPO Stroke Trial suggested a clinical benefit from EPO treatment in patients not receiving thrombolysis." (PMID 24918289, 2014). "Subsequently, an expanded trial of 460 patients revealed that a high number of stroke patients received tissue plasminogen activator (TPA) and that there was a significant increase in overall death rate with EPO treatment (42/256) compared with the placebo group (24/266)." (PMID 22567318, 2012). "The German Multicenter EPO Stroke Trial, which investigated safety and efficacy of EPO treatment in ischemic stroke, formally declared a negative result." (PMID 23272118, 2012). "Erythropoietin (EPO) is also recognized as a promising molecule to introduce neuroprotection, and encouraging results have been obtained from clinical trials involving stroke patients." (PMID 22216265, 2011). "In this Editorial we discuss potential reasons for the negative results of the German Multicenter EPO Stroke Trial, which contrasted the findings of a clinical pilot trial and several preclinical studies that showed beneficial effects of EPO." (PMID 20459870, 2010). "Neuroprotective, but not hematopoietic, variants of erythropoietin (EPO), such as Neuro-EPO, are promising candidates for treatment in the acute and subacute stroke phase." (PMID 21103797, 2010). "The future of non-hematopoietic EPO analogues for a further clinical development for stroke therapy will depend on the safety results of these trials." (PMID 20459870, 2010). "Using the intranasal delivery system, researchers have demonstrated neuroprotective effects in different animal models of stroke using erythropoietin (EPO) as a neuroprotector or other different types of EPO without erythropoiesis-stimulating activity." (PMID 19768354, 2009). "The hematopoietic growth factor erythropoietin (EPO) and its neuroprotective, but not hematopoietic, variants asialoEPO, carbamylated EPO (CEPO), and low sialic acid EPO (Neuro-EPO) are attractive candidates for stroke treatment." (PMID 19768353, 2009). "The incidence of stroke events was significantly greater in the high-ERI group than in the low-ERI group, which may be related to the procoagulant state induced by high-dose erythropoietin (EPO) and poor blood pressure control." (PMID 41244199, 2025). "In summary, this study indicates that genetically predicted long-term rises in endogenous EPO levels do not increase cardiovascular risk, with upper limits of 1.07, 1.15, and 1.07 for CAD, MI, and stroke, respectively, given a clinically relevant 2.2 unit rise in endogenous EPO levels." (PMID 36055212, 2022). "Furthermore, EPO mitigated stroke-induced activation of TAK1 and inflammasomes, indicating that EPO conveyed neuroprotection might be mediated via an EPO/TAK1/inflammasome axis." (PMID 34628598, 2022). "In addition, various neurotrophic factors secreted by astrocytes, such as nerve growth factor (NGF), brain-derived growth factor (BDNF), erythropoietin (EPO), vascular endothelial growth factor (VEGF), and glial derived neurotrophic factor (GDNF), are increased after stroke." (PMID 36159395, 2022). "Thus, the single administration of EPO immediately after the onset of ischemia, which is more similar to the clinical situation in stroke, is not expected to produce significantly different results." (PMID 33312715, 2020). "This may suggest that erythropoietin pretreatment decreases blood glucose in non-diabetic rats before stroke induction and exacerbates hyperglycemia resulting from stress response after IRI." (PMID 30719249, 2018).
Stroke (continued). "The negative findings of the German Multicenter EPO Stroke Trial could be a result of previously unknown side effects of EPO." (PMID 20459870, 2010). "Although either EPO or G-CSF has been shown to express neuroprotective and angiogenic effects in stroke animal models and limb ischemia, no report has yet focused on the enhanced ability of these two cytokines in combination to induce neuroplasticity and angiogenesis." (PMID 20404921, 2010). "One might consider that a further clinical stroke trial which excludes patients treated with rt-PA might show beneficial effects of EPO." (PMID 20459870, 2010). "In addition, the multicenter EPO stroke trial had to run over several years due to lack of funding in between, and exactly during this time, rtPA treatment in Germany rose dramatically (including numerous violations of rtPA indications in all but one of the trial centers)." (PMID 32546125, 2020). "Furthermore, the German multi-centre EPO Stroke Trial, a Phase II/III trial designed to reproduce the promising results of the earlier EPO Stroke Study (improved clinical recovery in EPO treated patients with ischemic stroke), was a negative trial that also raised safety concerns." (PMID 25643790, 2015). "Nonhematopoietic EPO analogues may represent a novel class of drugs for stroke therapy." (PMID 21766022, 2011). "The purpose of the Göttingen EPO Stroke Study (a pilot noncontrolled study) was to determine whether EPO would be safe due to the possibility of raised hematocrit and subsequently increasing the likelihood of further transient ischemic attacks during a 30-day follow-up period." (PMID 21943500, 2011). "However, neural-specific EPOR knockdown does not increase infarct volume following focal cerebral ischemia and therefore endogenous levels of EPO may not provide neuroprotection following stroke." (PMID 20339541, 2010). "However, the more recent German Multicenter EPO Stroke Trial, which was designed to reproduce the results of the Göttingen EPO Stroke Study, has unexpectedly documented that a combination of EPO and recombinant tissue plasminogen activator (tPA) is not advantageous and may even be detrimental." (PMID 21943500, 2011). "In a randomized controlled trial investigating the effect of erythropoietin in acute ischemic stroke, a slight increase in UCHL1 during the first three days after stroke was noted in the placebo group but not in the treatment group; however, no imaging data was available." (PMID 40900222, 2025). "In this respect, patients from the Göttingen EPO Stroke Study that did not receive thrombolysis but were treated with erythropoietin (EPO) showed significantly lower GFAP concentrations over 7 days, suggesting a beneficial effect of EPO in patients with IS." (PMID 39459548, 2024). "However, a direct interaction between EPO, TAK1, and inflammasomes, especially after stroke, has not been investigated to date." (PMID 34628598, 2022).
renal failure (169 papers, 2005 to 2025). "Sirtuin concentration was not influenced by age, sex, residual renal function, underlying etiology of renal failure, treatment with erythropoietin, or dialysis adequacy as measured by kt/V." (PMID 41009597, 2025). "First, they cause a dose-dependent suppression of erythropoietin, which is particularly problematic in patients with renal failure." (PMID 41012833, 2025). "In both groups, the underlying cause of kidney failure was varied, and all participants were receiving concurrent treatment with an erythropoietin stimulating agent (ESA)." (PMID 40025143, 2025). "As kidney failure progresses, the decline in serum concentration of erythropoietin parallels kidney excretory functional loss, and erythropoietin deficiency becomes more pronounced." (PMID 40025143, 2025). "Renal anemia is caused by reduced red blood cell (RBC) survival and erythropoietin (EPO) production due to renal failure." (PMID 36988549, 2023). "The mechanism in most patients is inadequate production of red blood cells due to either erythropoietin deficiency from accompanying renal failure or pronounced marrow replacement by myeloma cells." (PMID 35342422, 2022). "EPO was shown to promote antiinflammatory and M2 gene expression profiles in murine models of acute kidney injury and experimental colitis and was linked to macrophage efferocytosis in a model of kidney nephritis." (PMID 35389892, 2022). "In all cases, EPO was well tolerated and associated with remarkable recovery despite severe COVID-19 with multiple critical complications, including respiratory and renal failure, documented cytokine storm, and critical illness polyneuropathy." (PMID 34565332, 2021). "Renal failure was very uncommon as a cause of mid-term death, which supports our findings of EPO impact being independent from renal function." (PMID 33330669, 2020). "Extremely rare but serious side effects associated with long-term EPO administration in patients with chronic severe somatic diseases are thromboses at the site of dialysis in patients with kidney failure, seizure, and potential tumor growth." (PMID 30400939, 2018). "The main reason for the defective erythropoiesis in renal failure patients is the relative deficiency in erythropoietin (EPO) production by the peritubular cells of kidneys." (PMID 28747155, 2017). "Acute kidney injury, thromboembolic event, infection, malignancy and high dose erythropoietin usage are some of the risk factors that predisposed to NSF." (PMID 28738858, 2017). "Kidney failure also causes decrement in their capacity of producing hormones, particularly erythropoietin (EPO)." (PMID 28158274, 2017). "A role for cytokine mediated TEC protection following acute renal failure as caused by ischemia has been described previously for erythropoietin (EPO)." (PMID 21200435, 2010). "The probable explanation for the association in our study is that renal failure resulted in both increased transfusions and prescription of erythropoietin." (PMID 17002795, 2006). "However, exogenous EPO treatment to renal failure patients was associated with an increased risk of hypertension and cardiovascular events, and higher levels of endogenous EPO in healthy individuals were associated with higher incidence of heart failure." (PMID 38628440, 2024). "The liver may produce a certain amount of erythropoietin during renal failure; hence, liver dysfunction may be associated with impaired erythropoietin synthesis." (PMID 36767017, 2023). "Since store-operated calcium channel (SOC) signaling is one of the erythropoietin activated pathways, we aimed to investigate the association between the genetic polymorphisms of SOC signaling pathway and erythropoietin resistance in patients with renal failure." (PMID 33907089, 2021). "EPO may reduce kidney injury caused by ischemia/reperfusion, and it may facilitate kidney tubular regeneration by reducing severity of kidney failure." (PMID 32405372, 2020).
renal failure (continued). "The result of this study indicated that administration of rHu-EPO in dialysis patients afflicted to kidney failure may cause PRCA especially through intravenous injection." (PMID 28042550, 2017). "The aim of this single-site, randomized, case-controlled, and double-blind study was to investigate the effect of pre-emptive EPO administration on the incidence of postoperative acute kidney injury (AKI) in patients with risk factors for AKI undergoing complex valvular heart surgery." (PMID 24156702, 2013). "In our opinion, nephrotoxicity of cisplatin may be associated with more complications, such as acute kidney injury, electrolyte imbalance, or erythropoietin deficiency, than carboplatin, which influences the survival outcome in patients with advanced UTUC in real-world practice." (PMID 35207714, 2022). "It has been reported that erythropoietin can alleviate LPS‐induced microvascular injury by increasing the expression of VEGFR2 in septic acute kidney injury models." (PMID 40682486, 2025). "The new renal section lists three cases of PPOs in severe renal failure, i.e. calcitriol, phosphate binder and erythropoietin analogue (E1-3)." (PMID 40526338, 2025). "The patient started standard kidney failure treatment with chronic hemodialysis, bicarbonate substitution, potassium-binding resins, calcitriol, and erythropoietin." (PMID 40493263, 2025). "Erythropoietin (EPO), secreted by the kidneys, has neuroprotective effects; however, its level decreases during renal insufficiency, which can lead to reduced neurogenesis in the hippocampus." (PMID 41332466, 2025). "One contributing factor in some patients is reduced erythropoietin level, due to renal insufficiency resulting from MM." (PMID 39969535, 2025). "In patients with cardiorenal syndrome, renal insufficiency as a result of chronic venous hypertension leads to decreased production of erythropoietin (EPO) and subsequently decreased hematopoiesis." (PMID 40080287, 2025). "Renal hormones such as erythropoietin, which regulates the bone marrow's production of red blood cells, are thought to play a role in renal failure." (PMID 38764061, 2024). "Roxadustat, a hypoxia-inducible factor prolyl hydroxylase inhibitor, can stimulate endogenous erythropoietin production and regulate iron metabolism even in patients with kidney failure." (PMID 38086983, 2024). "The potential for using EPO in disease states, including the possibility of pharmacologically enhanced osteoblastic EPO to offset renal insufficiency, deserves further exploration." (PMID 38764792, 2024). "Erythropoietin (EPO), a cytokine that controls red blood cell production is often used in the settings of renal failure." (PMID 36873243, 2023). "The most elevated protein was erythropoietin, which is known to be markedly elevated in the initial inflammatory phase of critically ill patients; especially in the context of renal failure." (PMID 36766707, 2023). "It was assumed that the retrospective design of that study and the low dose of erythropoietin prevented from showing any positive effect of erythropoietin on reducing transfusions in acute kidney injury patients." (PMID 35279078, 2022). "We searched the literature for “recombinant human erythropoietin” or "erythropoietin" and “acute kidney disease” “acute renal failure” or or “acute kidney injury”." (PMID 35279078, 2022). "Renal failure led to decreasing erythropoietin (secreted by peritubular interstitial cells of the kidney) and vitamin D production, which adversely affected the immune system." (PMID 36618529, 2022). "The reduction in the synthesis of erythropoietin related to renal failure is the main reason for this abnormality." (PMID 35411265, 2022). "In response to acute kidney injury, EPO intervention can boost up the differentiation function of bone-marrow-derived mesenchymal stem cells and reverse their low secretion effect." (PMID 36139786, 2022).